IL1B (interleukin 1 beta)
Diseases named in the same sentence as IL1B in open-access papers (continued):
Sharing a sentence is not in itself a finding about the gene and the disease.
Obesity (continued). "To clarify the sequence of inflammatory factor expression and obesity, we examined the expression of IL‐1β and CXCL16 in mammary tissue of mice after 1 week of HFD before the notable difference in body weight became evident." (PMID 38145352, 2024). "With worsening obesity and metabolic dysfunction, the expression of inflammatory factors IL-1β and IL-6 in human subcutaneous white adipose tissue (sub-WAT) escalated, while genes related to adipogenesis were decreased." (PMID 38672517, 2024). "Obesity in EMS is intricately linked to persistent inflammatory states, a connection underscored by our observation of reduced pro-inflammatory markers IL-1β and TNF-α alongside an elevation in the anti-inflammatory cytokine IL-10 within the serum." (PMID 38689728, 2024). "IL1B, a pro-inflammatory cytokine, plays a crucial role in obesity-induced MASLD, participating in inflammation induction and cytokine production, central to MASLD pathology." (PMID 38755697, 2024). "Mice fed the fatty acid ester of palmitic and hydroxystearic acids (PAHSA) showed decreased TNF-α and IL-1β expression in macrophages when fed a high-fat diet and PAHSA were linked with obesity-related inflammation." (PMID 39335332, 2024). "The proinflammatory factors produced by M1-like macrophages, such as TNFα and IL-1β, are increased in islets in obesity and T2DM, and they decrease GSIS by inducing NF-κB or JNK activation in β cells after 16 or 24 h of treatment." (PMID 38693121, 2024). "On further analysis, we detected an inverse correlation between obesity of any degree and IL-1β concentration on the first day in blood plasma from all three vessels (IRA, peripheral artery and vein)." (PMID 39590595, 2024). "There were no clear sex differences in cytokine production capacity, although some cytokines were higher in females with obesity compared to males (for IL-1β, IL-6, TNF), in line with findings on activation markers by flow cytometry." (PMID 38741712, 2024). "High levels of adipokines, inflammatory modulators in obesity, are responsible for the secretion of pro-inflammatory cytokines, such as IFNγ, TNFα, IL-1β, IL-6, and IL-12." (PMID 39519568, 2024). "IL-1β serves as a potent proinflammatory cytokine, primarily generated by inflamed adipose tissue in humans, as well as immune cells in instances of obesity." (PMID 38999869, 2024). "Interleukin-1β (IL-1β) is a pro-inflammatory cytokine belonging to the IL-1 interleukin family and is upregulated in obesity." (PMID 39408157, 2024). "Risk factors for GD, such as obesity, are associated with increased numbers of resident adipose tissue macrophages that secrete pro-inflammatory cytokines, including TNF-α, IL-6, and IL-1β." (PMID 39456486, 2024). "In an obesity model, it has been seen that the cephalic phase of insulin release, impaired in obesity, is modulated by IL-1β originating from microglia." (PMID 39595866, 2024). "The volcano plot also confirmed significant downregulation of various genes in inflammation and obesity including IL-6, IL-1B, CCL2, PPARg, and Fabp4." (PMID 38512816, 2024). "The administration of COST resulted in the reduction of TNF-α, IL1-β, and IL-6 levels in an obesity cardiomyopathy mouse model." (PMID 38629103, 2024). "aimed to assess the relationship between IL-1β/Caspase-1, insulin sensitivity and early-stage obesity-related renal damage, namely hyperfiltration." (PMID 39469576, 2024). "In obesity, dysfunctional adipose tissue releases pro-inflammatory adipocytokines such as TNFα, IL-6, IL-1β, and free fatty acids (FFAs), which increase levels of pro-inflammatory factors." (PMID 39624218, 2024). "Obesity and overweightness are well-known proinflammatory metabolic disorders relating to high levels of inflammatory markers including interleukin (IL-)1β, IL-6, C-reactive protein, and tumor necrosis factor (TNF)α." (PMID 39337202, 2024).
Obesity (continued). "Although many cytokines and chemokines are involved in obesity-induced inflammation, TNF-α, IFN-γ, IL-6, and especially IL-1β have been closely linked to systemic insulin resistance." (PMID 39606781, 2024). "On the other hand, blocking IL-1β via antagonists in type 2 DM or obesity showed a significant reduction in systemic inflammation." (PMID 39063610, 2024). "In obesity, IL-1β is produced mainly after TLR4-mediated FFA activation of canonical inflammasomes, which is associated with increased expression of inflammation." (PMID 39063610, 2024). "It lowered colonic levels of malondialdehyde (MDA), IL-1β, and IL-6, reduced eosinophil infiltration, substance P, and inducible nitric oxide synthase (iNOS) expression indicating its inhibitory effects on obesity-induced colonic inflammation." (PMID 38629096, 2024). "HFD can also contribute to activating genes involved in this phenomenon, such as CD11b, MHC-II, CX3CR1, NLRP3, and IL-1β in the hippocampus and amygdala, favoring the inflammatory environment that contributes to the neurodegeneration observed in obesity." (PMID 36935429, 2023). "Glycolysis upregulation, as a driver of low‐grade inflammation in obesity, culminated in IL‐1β induction." (PMID 37823169, 2023). "The levels of other inflammatory cytokines, such as TNFα, MCP-1, IL-1β, and IL-8, also tend to increase in obesity." (PMID 37892420, 2023). "Pro-inflammatory cytokines such as TNF-α, IL-1β, and IL-6, which are mainly produced by immune cells and adipocytes, play a vital role in the pathogenesis of obesity and OA." (PMID 37703108, 2023). "Especially, the accumulation of NLRP3 promoted obesity-related impairment of spermatogenesis and testosterone synthesis by triggering interleukin-1β (IL-1β) secretion." (PMID 37935689, 2023). "Inflammatory cytokines, including interleukin (IL)-6, tumor necrosis factor alpha (TNFα), and IL-1β, have been shown promote the expansion of myeloid progenitor cells and are produced by both adipocytes and macrophages in obesity." (PMID 38041006, 2023). "The 60% fat diet increased the IL-1β level in only male liver lysates, suggesting the IL-1β production is associated with the extent and phenotype of HFD-induced obesity." (PMID 36810096, 2023). "For IL-1β and IL-6, two-way ANOVA revealed significant effects of obesity (F = 7.462; p = 0.0258 for IL-1β; F = 6.943; p = 0.0299 for IL-6)." (PMID 37892420, 2023). "In adolescents with obesity, the decrease in IL-10 and the increase in IL-1β stimulate hepcidin release, while in childhood obesity, the increase in miRNA-122 can limit hepcidin levels." (PMID 38140340, 2023). "The additional factors that contribute to the AMPK activation after combined treatment are increased cytokines in these animals, since Il1b, as obesity-related, and Il6, as a muscle energy sensor, contribute to increased AMPK activity." (PMID 37371678, 2023). "The pro-inflammatory ATMs are one of the key cell types responsible to produce pro-inflammatory cytokines such as TNF-α, IL-1β, and IL-6, which contribute to obesity-related adipose tissue inflammation." (PMID 37153549, 2023). "Mounting studies have demonstrated that macrophages are recruited into adipose tissue and secrete inflammatory cytokines such as IL-1β and TNF-α during obesity, thereby causing local and systemic inflammation." (PMID 38070059, 2023). "NLRP3 inflammasome is activated by ceramides sensing, inducing IL-1β production through caspase-1 activation, contributing to obesity-induced inflammation and insulin resistance." (PMID 37819510, 2023). "Previous studies have demonstrated that obesity is correlated with the enhanced secretion of inflammatory cytokines, including IL-6, IL-1β, and TNF-α." (PMID 38035300, 2023). "Many of the common secreted upstream regulators we identified, such as TNF, IL-1β, IFN-γ, IL-18, CD40L, IL-6, EGF, TGFβ, and IL-21, were previously reported to be associated with obesity and metabolic dysfunction." (PMID 36880999, 2023).
Obesity (continued). "Differences between the overweight, obese and severe obesity groups were observed for IL-1β, IL-6, and IL-10." (PMID 37336969, 2023). "IL‐1β is considered a strong pro‐inflammatory cytokine and has been shown to play a role in obesity‐induced liver steatosis by up‐regulating gene expression of lipogenic enzymes." (PMID 37177862, 2023). "Obesity is regarded as a kind of chronic inflammation and can increase the levels of TNFα, IL-1β, IL-6, and IL-18 within adipose tissue and systemically, such as through inflammasome activation in macrophages." (PMID 37526777, 2023). "For instance, supplementation with polysaccharides extracted from green walnut husk reduced the levels of pro‐inflammatory cytokines TNF‐α and IL‐1β, via gut microbiota regulation, which is helpful to inhibit the occurrence of obesity." (PMID 37823169, 2023). "Caloric restriction- and weight loss-induced insulin sensitivity was associated with decreased NLRP3 and IL-1β expression in subcutaneous adipose tissue, further suggesting that NLRP3 is associated with diabetes and obesity." (PMID 36834674, 2023). "Excessive dietary intake of SFA is usually associated with increased obesity-related hepatic inflammatory plasma markers such as ALT and AST, as well as cytokines, such as TNFα and IL-1β, involved in the inflammatory response." (PMID 38004155, 2023). "In a study on mice with obesity and asthma, vitamin D3 levels were related to the increased expression of IL-1β mRNA and NLRP3 mRNA in lung tissue." (PMID 38276294, 2023). "IL-1β, which is produced and detected in meta-inflammation of obesity, alters the production of inflammatory cytokines and chemokines in pre-adipocytes." (PMID 37336969, 2023). "Proinflammatory cytokines TNFα, IL-1β, and IL-6, are produced by macrophages and adipocytes, the primary cells involved in obesity and metabolic disorders." (PMID 36830566, 2023). "The authors claim that activation of inflammasome in ATMs during obesity induces the release of IL-1β which interferes with the metabolic capacity of bystander adipocytes." (PMID 36175539, 2023). "One proposed mechanism underlying the link between obesity, inflammation, and CRC risk is through the secretion of inflammatory cytokines such as TNF-α, IL-1β, IL-6, and monocyte chemoattractant protein (MCP)-1 by adipose tissue-derived cells." (PMID 36839339, 2023). "Several seminal papers described the involvement of pro-inflammatory cytokines, namely, IL-1β, in the pathogenesis of obesity and diabetes." (PMID 36994095, 2023). "All these pro-inflammatory markers were significantly upregulated in participants with obesity compared with lean individuals (p < 0.05), with an observed maximum threefold difference for IL1β (Fig. S3D2, p < 0.001)." (PMID 37076885, 2023). "Of relevance in terms of obesity, adipose tissue-derived interleukin (IL)-1β has been shown to stimulate proliferation of bone marrow progenitor cells." (PMID 37209535, 2023). "The effect of obesity on the equine uterus has not been well defined, although gene expression in the endometrium was altered even after short-term obesity, showing a pro-inflammatory profile with increased expression of TNFα and IL1β." (PMID 35563743, 2022). "In this review article, we will present the possible links between inflammasome-mediated cytokines, obesity-associated NASH, and HCC development, and we will also discuss approaches to using IL-1β and IL-18 as therapeutic targets in the context of HCC." (PMID 36289606, 2022). "Both DCE and DCT significantly decreased the obesity-induced overexpression of IL-1β (p < 0.01 and p < 0.05, respectively)." (PMID 36139877, 2022). "In a variety of rodent models, prediabetes and obesity were ameliorated by inhibition of IL‐1 signalling or antibodies antagonizing IL‐1β." (PMID 36101976, 2022).
Obesity (continued). "The mRNA levels of Cd8, iNOS, TNF-α, and IL-1β were increased in obese CCL5 KO mice than in obese WT mice, indicating that CCL5 deficiency also exacerbates liver inflammation in obesity." (PMID 36713454, 2022). "When tested in mice, treatment with MCC950 attenuated the increase in body weight induced by an HFD, reduced IL-1β concentrations in adipose tissue, prevented insulin resistance, and reduced airway inflammation induced by obesity." (PMID 35806353, 2022). "Obesity-induced increase in IL-1β levels, mostly in diabetes patients, and the improvement in insulin sensitivity was associated with decrease in cytokine levels." (PMID 35889863, 2022). "Over 15 years ago, it was stated that IL-1β was released by human adipocytes and was regulated by TNFα in obesity." (PMID 35139823, 2022). "Obesity is associated with inflammatory adipokines including leptin, resistin, lipocain 2, IL-6, TNF-α, IL-1β, and IFN-γ." (PMID 35626330, 2022). "Chronic low-grade inflammation characterized by higher levels of Il-1b and Il-6 has been reported to be one of the hallmarks of obesity-induced insulin resistance." (PMID 35967777, 2022). "This suggests that inflammatory cytokines contribute to IVDD phenotypes rather than physical factors, and our combined stimulation results of hResistin and IL-1β can be interpreted as results from adipokines and inflammatory cytokines in obesity." (PMID 35624126, 2022). "Studies using a rodent model of neuropathic pain and obesity demonstrated that tDCS can prevent increases in IL-1β, TNF-α and IL-10 triggered by chronic constriction injury in a neuropathic pain model or hypercaloric diet in a model for obesity." (PMID 36620466, 2022). "In both human and animal models, diet-induced obesity is associated with increased circulating inflammatory markers such as TNF-α, IL-1β, and IL-6, which represent a key step in the development of insulin resistance in peripheral organs." (PMID 35871167, 2022). "These in vitro findings are consistent with studies conducted in individuals with airway inflammation, where serum levels of both leptin and IL-1β were shown to increase with BMI and were thus higher in subjects with obesity." (PMID 35806353, 2022). "In order to elucidate the mechanism behind the increased pro-inflammatory [Ca2+]ex-induced IL-1β release in visceral AT in obesity, RNA expression was analysed by realtime PCR in the tissue samples." (PMID 35931812, 2022). "Consistent with the heightened activation of PRRs, ELISA showed that serum cytokine concentrations of TNF-α, IFN-γ, IL-1β, IL-6, and IL-17A were significantly induced with obesity, as was anti-inflammatory TGF-β and IL-10." (PMID 36406423, 2022). "Pro-inflammatory cytokines such as IL-1β, IL-6, and TNF-α closely interact with immune and metabolism regulatory systems and modulate the risk for diabetes mellitus type II and obesity." (PMID 35206947, 2022). "The AZGP1 gene is involved in the TNF-alpha and IL-1 beta (IL-1b) pathways, which are involved with the occurrence of dyslipidemia and inflammation in adipocytes, leading to the development of obesity and type 2 diabetes diseases." (PMID 35804531, 2022). "Mostly in freshly isolated PBMC from individuals with obesity which showed significantly higher expression levels of pro-inflammatory cytokines (IL-1β, MCP-1, IL-8, and IL-6) as compared to control subjects." (PMID 35896710, 2022). "Focusing research on subjects with both airway inflammation and obesity, recent studies have shown that IL-1β serum and sputum levels are correlated with BMI and are an important risk factor for the exacerbation of symptoms." (PMID 35806353, 2022). "Supplementation with WTE prevented the obesity-induced changes in the gene expression of IL-1β, IL-6 and NOX-4 (p < 0.05 for all)." (PMID 36009292, 2022). "It is up-regulated in obesity and promotes inflammation through inflammatory cytokines IL-1β and TNF-α." (PMID 36145151, 2022).
Obesity (continued). "Of note, there was a marked obesity-induced atrial Il-1β expression, which was abolished with genetic inhibition of SGK1." (PMID 35998035, 2022). "LGWWJX protects obesity-related asthma through mechanisms including the inhibition of the IL-1β/ILC3/IL-17A/AHR axis, anti-inflammatory effects, weight loss, and the regulation of lipid metabolism." (PMID 36051916, 2022). "IL-1β is elevated in obesity and induces insulin resistance by inhibiting the insulin signaling pathway." (PMID 36230963, 2022). "It should be noted that NLRP3 inflammasome-derived IL-1β plays an important role in the obesity model: this cytokine is upregulated in obesity, and blockade of IL-1β abolishes obesity-induced ILC3-mediated AHR." (PMID 36466877, 2022). "[Ca2+]ex-induced IL-1β release was investigated in monocyte-derived macrophages (MDM) generated from peripheral blood of patients with obesity and from normal-weight controls." (PMID 35931812, 2022). "Metabolic stress, in the form of obesity, saturated fatty acids (SFAs), cholesterol, reactive oxygen species, and/or uric acid promote IL-1β signaling." (PMID 35276849, 2022). "IL-1β is a strong proinflammatory cytokine, which is mainly produced by inflamed human adipose tissue and also immune cells in obesity but also impairs insulin signalling and increases lipolysis." (PMID 35883817, 2022). "One possibility to interpret this finding is, that equal concentrations of [Ca2+]ex induce more IL-1β release in obesity than in controls." (PMID 35931812, 2022). "The relative mRNA expression of IL-1β was also significantly higher in the lung tissues in the context of obesity (HFC vs LFC, HFP vs LFP, p ≤ 0.05)." (PMID 36060644, 2022). "In our study, obesity-induced damage to the heart was associated with NF-κB activation and increased in ICAM-1, PECAM-1, TNF-α, IL-1β, and IL-6 expression levels." (PMID 35625374, 2022). "A study investigating the role of NLRP3 inflammasome in obesity and obesity-induced inflammation shows that the mRNA levels of IL-1β and NLRP3 in the visceral adipose tissue are positively correlated with BW of C57BL/6 mice." (PMID 36142842, 2022). "When visceral and subcutaneous tissue sample were analysed separately, a significantly higher [Ca2+]ex-induced IL-1β release was detectable in visceral AT samples than in subcutaneous AT from the same people with obesity." (PMID 35931812, 2022). "During obesity, neutrophils have high neutrophil elastase, neutrophil alkaline phosphatase, myeloperoxidase, IL-6, IL-1β, IL-12, IL-8, and TNF-α, and low expression of IL-10, which favors activation of M1 macrophages and development of chronic inflammation." (PMID 36230963, 2022). "Because we were focusing on inflammatory cytokines that play a major role in developing obesity, we quantified the level of IL-1β, IL-6, IL-17A, IFN-γ and TNF-α in the plasma of lean, HFD and GaELNs treated HFD mice." (PMID 35154484, 2022). "IL-1β and TNFα were identified as inducers of S100A9 in epidermis and dWAT while obesity-associated factors such as high glucose, insulin or SFA do not affect S100A9 expression." (PMID 35198063, 2022). "Sankey plot analysis connected a total of 25 miRNAs that are known to be regulators of canonical inflammatory genes involved in obesity, such as TNF-α, IL-6, and IL-1β, to the list of L_Ag-associated DEMs and O_Ag-associated DEMs." (PMID 35798800, 2022). "Accordingly, levels of pro-inflammatory cytokines, including IL-1β and IL-18, have been found to be increased in subjects with obesity or respiratory diseases." (PMID 35806353, 2022). "We therefore supposed an indirect mechanism of S100A9 overexpression during inflammation in obesity that is mediated by macrophages as one important source of TNFα and IL-1β." (PMID 35198063, 2022). "Overproduction of interleukin-6 (IL-6) and interleukin-1β (IL-1β) is an important feature of obesity, which contributes significantly to IR." (PMID 35721805, 2022).